MAOB (monoamine oxidase B)
Diseases named in the same sentence as MAOB in open-access papers (continued):
Sharing a sentence is not in itself a finding about the gene and the disease.
COVID-19 (4 papers, 2021 to 2024). A disease caused by infection with severe acute respiratory syndrome coronavirus 2. "Another class of drug that showed frequent interaction with COVID-19 treatment, mainly antitussives, was monoamine oxidase B (MAO-B) inhibitors." (PMID 38887342, 2024). "Our results showed that SARS-CoV-2 infection did not affect the expression of DBH and VMAT2, but elevated, however, the mRNA levels of MAOA and MAOB in infected cells and in the whole blood samples of hospitalized COVID-19 patients." (PMID 36611805, 2022). "Similar to the DDC mRNA expression, the presence of comorbidities did not affect the mRNA levels of MAOA and MAOB in the whole blood samples of hospitalized COVID-19 patients." (PMID 36611805, 2022).
insomnia (4 papers, 2021 to 2025). A sleep disorder characterized by difficulty in falling asleep and/or remaining asleep. "We could predict the role of VVO in modulating the serotonergic synaptic pathway in the treatment of insomnia, and this modulation was associated with MAOB, MAOA, PTGS2, HTR2A, and SLC6A4." (PMID 40004189, 2025). "The results from the PPI analysis show that the targets of VVO for the treatment of insomnia mainly involve MAOB, DRD2, MAOA, IL1B, PTGS2, HTR2A, SLC6A4, and ESR1." (PMID 40004189, 2025). "In summary, our research findings have elucidated that VVO treats insomnia through a variety of components and multiple targets, with MAOB, MAOA, SLC6A4, HTR2A, and others at serotonergic synapses playing a vital role in the process of VVO treating insomnia." (PMID 40004189, 2025).
ischemia (4 papers, 2018 to 2025). A hypoperfusion of the BLOOD through an organ or tissue caused by a PATHOLOGIC CONSTRICTION or obstruction of its BLOOD VESSELS, or an absence of BLOOD CIRCULATION. "The cardiomyocyte-specific knockout of monoamine oxidase B (MAO-B) reduced myocardial infarct size and mortality after the ischemia/reperfusion protocol in male mice but had no protective effect in females, which exhibited lower infarct sizes in wild-type controls." (PMID 40722993, 2025).
liver cancer (4 papers, 2023 to 2026). An epithelial or non-epithelial malignant neoplasm that arises from the liver. "MAOB is involved in the biosynthesis of endogenous geranyl valeric acid (GGA) through geranyl geraniol oxidation, while GGA is a prophylactic agent for secondary primary liver cancer." (PMID 38429802, 2024).
myocardial infarct (4 papers, 2018 to 2026). "Recently, a study using rasagiline mesylate, a monoamine oxidase B inhibitor, prevented post-myocardial infarct LV remodelling by activating circadian gene expression." (PMID 35625658, 2022).
non-small cell lung carcinoma (4 papers, 2016 to 2025). A group of at least three distinct histological types of lung cancer, including non-small cell squamous cell carcinoma, adenocarcinoma, and large cell carcinoma. "In non-small cell lung cancer (NSCLC), MAOB serves as a diagnostic/prognostic marker, and its inhibition enhances radiosensitivity." (PMID 40821817, 2025). "Additionally, Danshensu inhibited MAOB activity and NF-κB signalling, and ultimately enhanced the radiation efficacy of non-small-cell lung cancer." (PMID 36678509, 2022).
pharyngeal cancer (4 papers, 2014 to 2025). "MAOB at-risk alleles (rs6324 (G)) were associated with the risk of oral and pharyngeal cancers and OPMD." (PMID 34209963, 2021). "Subjects with MAOA rs1137070 (T-allele) and MAOB rs6324 (G-allele) had a significantly increased risk of oral and pharyngeal cancers (AOR = 45.56; 95% CI, 18.51–112.17) and risk of OPMD (AOR = 70.59; 95% CI, 14.17–351.78)." (PMID 34209963, 2021). "We found that BQ chewers with MAOB (rs6324) risk G-allele had a significantly synergistic risk of oral and pharyngeal cancers (AOR = 307.03; 95% CI, 97.43–967.54)." (PMID 34209963, 2021). "Compared to the healthy control group (MAOB (rs6324) A-allele), the MAOB (rs6324) risk G-allele was significantly related to the risks of oral cavity and pharynx cancers (AOR = 13.00, 95% CI = 7.35–22.98) and OPMD (AOR = 37.45, 95% CI = 11.94–117.46)." (PMID 34209963, 2021). "Likewise, BQ chewers with MAOB rs1799836 (T-allele) had a prominently synergistic risk of oral and pharyngeal cancers (AOR = 22.60; 95% CI, 7.13–71.62) and risk of OPMD (AOR = 6.32; 95% CI, 1.21–33.08)." (PMID 34209963, 2021). "Carriers of the MAOA rs6323 G-allele, MAOB rs6324 G-allele, and COMT rs4633 C/C-genotype had a prominently increased risk of oral cavity and pharynx cancers (AOR = 56.99; p < 0.001)." (PMID 34209963, 2021). "In terms of MAOA, MAOB, and COMT, subjects with the MAOA rs6323 G-allele, MAOB rs6324 G-allele, and COMT rs4633 C/C-genotype had a significantly increased risk of oral and pharyngeal cancers (AOR = 56.99; 95% CI, 15.82–205.31)." (PMID 34209963, 2021). "In terms of MAOB and COMT, subjects with MAOB rs6324 (G-allele) and COMT rs4633 (C/C genotype) had a significantly increased risk of oral and pharyngeal cancers (AOR = 39.27; 95% CI, 15.66–98.47)." (PMID 34209963, 2021). "Subjects with the MAOA rs1137070 T-allele, MAOB rs6324 G-allele, and COMT rs4633 C/C-genotype had a significantly increased risk of oral and pharyngeal cancers (AOR = 78.62; 95% CI, 20.37–303.45)." (PMID 34209963, 2021). "Our previous studies suggested that MAO-A and monoamine oxidase B (MAO-B) variants are associated with oral and pharyngeal cancer risks." (PMID 29376073, 2017). "Moreover, the risk of oral cavity and pharynx cancers was much higher in carriers of the MAOA rs6323 G-allele and MAOB rs6324 G-allele." (PMID 39714760, 2025). "We assume that three biomarker (MAOA, MAOB, and COMT) variants may contribute to oral and pharyngeal cancers occurrence and may be implicated in the induction of arecoline." (PMID 34209963, 2021).
Akinesia (3 papers, 2022 to 2026). Inability to initiate changes in activity or movement and to perform ordinary volitional movements rapidly and easily. "Morning akinesia occurred despite adjunctive treatment added to levodopa (85 % on dopamine agonists, 50 % on catechol-O-methyltransferase [COMT] inhibitors, and 92 % on monoamine oxidase-B [MAO-B] inhibitors)." (PMID 36033905, 2022).
cocaine addiction (3 papers, 2009 to 2026). "It has been observed that the MAOB gene is involved in dopaminergic synapses, serotonergic synapses, and cocaine addiction pathways." (PMID 41601963, 2026).
colon cancer (3 papers, 2020 to 2025). "The data revealed that MAOB exerted a strong and significant positive correlation with these mesenchymal markers in colon cancer samples (all p-values < 0.0001)." (PMID 32316576, 2020). "Additionally immunohistochemical detection of colon cancer micro array revealed that the expression of serotonin metabolism-related enzymes (TPH1, SERT, MAOA, and MAOB) were overexpressed in human colon cancer tissues than in the adjacent normal tissues." (PMID 34006301, 2021). "Importantly, the prognostic value of MAOB expression was better than that of the T or N stage in these colon cancer patients." (PMID 32316576, 2020). "In addition, MAOB expression was also found to be higher in the C85 colon cancer cell line treated with methotrexate, an anti-folate drug." (PMID 32316576, 2020). "Because a strong association between MAOB expression and a poor prognosis was observed, we therefore hypothesized a connection between MAOB and the EMT pathway in colon cancer." (PMID 32316576, 2020). "Mechanically, MAOB might promote colon cancer progression through inducing EMT progression." (PMID 32316576, 2020).
conduct disorder (3 papers, 2017 to 2022). A disorder diagnosed in childhood or adolescence age group characterized by aggressive behavior, deceitfulness, destruction of property or violation of rules that is persistent and repetitive, and within a one year period. "Our earlier population based analysis on this group of subjects revealed significant contribution of MAOA rs6323 and MAOB rs56220155 in ADHD associated conduct disorder as well as ODD." (PMID 28982350, 2017). "Building on this evidence, we assessed whether conduct disorder (CD), juvenile delinquency adjudications, or detention in a correctional facility were associated with either platelet MAO-B activity or the MAOB rs1799836 polymorphism." (PMID 33203099, 2020).
coronary heart disease (3 papers, 2018 to 2023). "Other important findings showed that MAOB-related ROS production promotes a pro-oxidative status of endothelial dysfunction in coronary heart disease patients, and the MAOB inhibitor selegiline may be useful in restoring the endothelial response." (PMID 37299505, 2023).
Hallucinations (3 papers, 2015 to 2022). Perceptions in a conscious and awake state that, in the absence of external stimuli, have qualities of real perception. "At age 48, visual hallucinations developed, which did not improve despite withdrawal of dopamine agonist and monoamine oxidase B inhibitor." (PMID 26306801, 2015).
head and neck squamous cell carcinoma (3 papers, 2021 to 2025). A squamous cell carcinoma that arises from any of the following anatomic sites: lip and oral cavity, nasal cavity, paranasal sinuses, pharynx, larynx, and salivary glands. "Beyond ccRCC, MAOB was reported to be a tumor suppressor and is downregulated in head and neck squamous cell carcinoma (HNSCC)." (PMID 41338163, 2025).
lung adenocarcinoma (3 papers, 2024 to 2025). A carcinoma that arises from the lung and is characterized by the presence of malignant glandular epithelial cells. "In our study, we found the characteristic genes that affected lung adenocarcinoma through the propionate pathway included LDHA, KYNU, SLC2A1, CFTR, and MAOB." (PMID 41003841, 2025).
asthma (2 papers, 2023 to 2026). "Therefore, this study aimed to investigate platelet 5-HT levels, platelet MAO-B activity, and the potential associations of HTR2A, HTR2C, and MAOB gene polymorphisms in adult asthma patients and healthy control subjects, as well as in asthma patients of different severity and phenotypes." (PMID 37238670, 2023). "We further investigated the potential association of MAOB (rs1799836 and rs6651806), HTR2A (rs6314 and rs6313), and HTR2C (rs3813929 and rs518147) gene polymorphisms with asthma." (PMID 37238670, 2023). "Such associations of the MAOB gene polymorphisms with asthma and asthma severity have not yet been researched." (PMID 37238670, 2023). "However, we know that such associations of HTR2A, HTR2C, and MAOB gene polymorphisms with asthma phenotypes have not yet been investigated." (PMID 37238670, 2023). "Only the healthy subjects, but not the asthma patients, carrying the MAOB rs1799836 TT genotype had significantly lower platelet MAO-B activity than the C allele carriers." (PMID 37238670, 2023). "Only healthy subjects, but not asthma patients, carrying the MAOB rs1799836 TT genotype had significantly lower platelet MAO-B activity than the C allele carriers." (PMID 37238670, 2023).
endometritis (2 papers, 2016 to 2020). An acute or chronic, usually bacterial infectious process affecting the endometrium. "There are 92 genes, including PTHLH, INHBA, DAPL1, and SERPINA1, which were significantly highly regulated and 111 genes which had significantly poorly regulated expression levels, including MAOB, CXCR4, HSD11B, and BOLA, as recorded in clinical endometritis." (PMID 33426032, 2020). "The expression patterns of only 28 genes in subclinical endometritis have been substantially altered, of which 26 genes including PTHLH, INHBA, DAPL1, MAOB, CXCR4, and TGIF1 were identified in both subclinical and clinical endometritis." (PMID 33426032, 2020).
endothelial dysfunction (2 papers, 2023 to 2025). In vascular diseases, endothelial dysfunction is a systemic pathological state of the endothelium (the inner lining of blood vessels) and can be broadly defined as an imbalance between vasodilating and vasoconstricting substances produced by (or acting on) the endothelium. "Taken together, our findings showed that MAOB controlled endothelial oxidative stress homeostasis, and revealed the anti-atherosclerotic effect of selegiline by ameliorating endothelial dysfunction and modulating the composition and function of gut microbiota." (PMID 37299505, 2023). "To determine the role of MAOB in an HFD-induced oxidative stress and endothelial dysfunction, we first examined MAOB expression in mice." (PMID 37299505, 2023). "We found that MAOB siRNA significantly attenuated cellular oxidative stress levels and alleviated endothelial dysfunction induced by PA treatment." (PMID 37299505, 2023). "The increased MAOB expression in vascular endothelial cells suggested an important role of endothelial MAOB in the regulation of the HFD-induced endothelial dysfunction." (PMID 37299505, 2023). "It has been shown that inhibition of MAOB restored endothelial dysfunction and reduced atherosclerosis by inhibiting several key steps (ROS, adhesion molecules and proinflammatory cytokines) in its pathogenesis." (PMID 37299505, 2023). "Moreover, inhibition of MAOB by selegiline significantly ameliorated endothelial dysfunction and reduced atherosclerotic burden in HFD-fed ApoE−/− mice." (PMID 37299505, 2023). "Due to the crucial role of MAOB in endothelial dysfunction and atherosclerosis, it is worthwhile investigating whether MAOB inhibitors can exert beneficial effects on ACVDs." (PMID 37299505, 2023). "To determine whether MAOB activation plays an essential role in oxidative stress and endothelial dysfunction in PA-treated HUVECs, we first silenced the MAOB gene by transfecting MAOB siRNA into HUVECs." (PMID 37299505, 2023).
esophageal cancer (2 papers, 2020 to 2021). A primary or metastatic malignant neoplasm involving the esophagus. "DE VEGFA, FOSL1, MAOB, SDR16C5, RP11-58O9.2, RP11-667F14.1, and RP11-288A5.2 in hyperplastic tissues may serve as genetic targets for preventing stent restenosis in esophageal cancer." (PMID 33391336, 2020). "VEGFA, FOSL1, MAOB, SDR16C5, RP11-58O9.2, RP11-667F14.1, and RP11-288A5.2 may be served as genetic targets for preventing stent restenosis in esophageal cancer." (PMID 33391336, 2020).
Gliosis (2 papers, 2018 to 2021). Gliosis is the focal proliferation of glial cells in the central nervous system. "Monoamine oxidase B (MAO-B) activity is also reported to be increased in association with gliosis, which can result in higher levels of hydrogen peroxide and oxidative stress for vulnerable neurons affected by NDDs." (PMID 29098902, 2018).
liver fibrosis (2 papers, 2022 to 2024). "MAO exists as two isoenzymes, namely, monoamine oxidase A (MAO-A) and monoamine oxidase B (MAO-B), with the latter implicated in collagen fiber formation and closely associated with liver fibrosis." (PMID 38707500, 2024). "For instance, monoamine oxidase B (MAO-B) has been found to be overexpressed in patients with early liver fibrosis, rendering it a promising early marker for liver fibrosis." (PMID 38707500, 2024). "MAOB is considered an ideal marker for the diagnosis of hepatic fibrosis, and the level of MAOB was obviously increased in the sera of patients with early liver fibrosis." (PMID 36676934, 2022). "Moreover, CYP1A1, ODC1 and MAOB may be potential targets related to the anti-liver fibrosis effects of dehydrocarptin, tetrahydropalmatine and palmatine, respectively." (PMID 36676934, 2022). "Furthermore, CYP1A1, ODC1 and MAOB comprise the intersection of TACS targets, metabolic pathway targets and disease-related targets, and dehydrocavidine, tetrahydropalmatine and palmatine are considered as potential active compounds for CCl4-induced liver fibrosis therapy." (PMID 36676934, 2022).
meningioma (2 papers, 2016 to 2020). A generally slow growing tumor attached to the dura mater. "MAOB showed a distinct increase in expression in grade III meningiomas consistent with WB findings, generally displaying moderate immunostaining, whereas grade I tumours showed either weak or absent expression." (PMID 33167358, 2020). "Lastly, we revealed a substantial amount of concordantly upregulated proteins to be associated with one or more FDA-approved drugs, among which was the validated protein, MAOB, encouraging drug repurposing for meningioma treatment." (PMID 33167358, 2020). "While RBP1 did not exhibit a rise in protein expression between grade III and grade I meningiomas, MAOB presence was found to be higher in grade III tumours by both WB and IHC." (PMID 33167358, 2020). "Although we detected some CD68+ cells, the widespread expression of MAOB throughout the tissue suggests that the majority of immunostaining is genuinely derived from meningioma cells themselves." (PMID 33167358, 2020). "Although a pathophysiological role of MAOB in high-grade meningiomas has yet to be determined, its association to 19 FDA-approved drugs suggests MAOB may prove to be a strong candidate as a molecular target in these tumours." (PMID 33167358, 2020). "It has been reported that compared to normal brain tissue, MAOB activity is significantly greater in tissue from GBM, low-grade astrocytomas, and anaplastic astrocytomas, but but meningioma tissue shows no increase in MAOB activity with respect to control brain tissue." (PMID 26689994, 2016).
Nicotine addiction (2 papers, 2009 to 2017). "Nicotine addiction induces a long-lasting effect due to the demethylation of the monoamine oxidase-B (MAOB) gene promoter, which results in a persistently high concentration of platelet MAO-B in former smokers who quit smoking an average of 13 years ago." (PMID 29023416, 2017).
oral squamous cell carcinoma (2 papers, 2021 to 2025). "In silico studies introduced LN as inhibitors of Akt1 and Akt2 with strong binding affinities of 11.5 kcal/mol and 11.1 kcal/mol, respectively, with no affinity toward MAOB, which can be an ideal candidate for oral squamous cell carcinoma treatment." (PMID 34832886, 2021). "It was reported that Akt1 and Akt2 inhibitors can lead to oral squamous cell carcinoma treatment with no affinity toward monoamine oxidase B (MAOB)." (PMID 34832886, 2021).
orthostatic hypotension (2 papers, 2022 to 2024). Sudden fall of the blood pressure of at least 20/10 mm Hg when a person stands up. "Monoamine oxidase B inhibitors have also been reported to induce orthostatic hypotension in PD patients." (PMID 39199470, 2024).
adrenal pheochromocytoma (1 paper, 2023). "MAOB (S) in PCC showed higher H-scores when the grading of adrenal pheochromocytoma and paraganglioma (GAPP) score was 3 or higher (p = 0.027)." (PMID 37509535, 2023).
alcohol addiction (1 paper, 2021). "In this present study we found a higher frequency of the 184 bp MAOB VNTR (GT)n polymorphism in subjects with cocaine or opiate addictions compared to subjects with an alcohol addiction." (PMID 34679329, 2021). "Our results show differences in a MAOB gene marker in polyconsumer subjects with an addiction to cocaine or opiates compared to polyconsumers with an alcohol addiction." (PMID 34679329, 2021). "However, no direct associations between specific MAOB polymorphisms and vulnerability to alcohol addiction have been observed, and we could find no research indicating any relationship between MAOB gene polymorphisms and cocaine or opiate addictions." (PMID 34679329, 2021).
astrocytomas (1 paper, 2016). "The gemistocytic astrocytoma had MAOB levels similar to the two grade II astrocytomas." (PMID 26689994, 2016). "The MAOB level of two grade II astrocytomas was greater than 2.5 times that of the control." (PMID 26689994, 2016). "However the slope of the fit is inversed in the two groups of tumors; that is, MAOB positively correlated with Sp3 levels in the astrocytoma and aberrant GBM and is negatively correlated as in the case of the 16 mainstream GBM, hence the opposing slopes of the black and red fitted lines." (PMID 26689994, 2016).